MICA (MHC class I polypeptide-related sequence A)
Description:
Widely expressed membrane-bound protein which acts as a ligand to stimulate an activating receptor KLRK1/NKG2D, expressed on the surface of essentially all human natural killer (NK), gammadelta T and CD8 alphabeta T-cells. Up-regulated in stressed conditions, such as viral and bacterial infections or DNA damage response, serves as signal of cellular stress, and engagement of KLRK1/NKG2D by MICA triggers NK-cells resulting in a range of immune effector functions, such as cytotoxicity and cytokine production.
Synonyms: MIC-A; PERB11.1
Gene: Protein-coding gene on chromosome 6 (31,399,784 to 31,415,315, forward strand). Ensembl gene ENSG00000204520.
Subcellular location: Cell membrane; Cytoplasm
Genetic constraint (gnomAD): Loss-of-function variants: 18 observed, 34.15 expected, observed/expected ratio (o/e) 0.53, 90% interval 0.36 to 0.78. The upper end of that interval is the gene's LOEUF score, 0.78, which puts it in group 3 of 6, group 1 being the genes least tolerant of losing a copy. Missense variants: 325 observed, 393.31 expected, observed/expected ratio (o/e) 0.83, 90% interval 0.75 to 0.91. Synonymous variants: 132 observed, 149.55 expected, observed/expected ratio (o/e) 0.88, 90% interval 0.76 to 1.02.
Homologues: Orthologues: chimpanzee MICB (83% identical), macaque MIC1 (69% identical), mouse Mill1 (31% identical), mouse Mill2 (30% identical), rat Mill1 (27% identical), rat Micb (25% identical). Paralogues in human: MICB (81% identical), HFE (28% identical), HLA-E (28% identical), HLA-F (28% identical), HLA-C (28% identical), HLA-A (27% identical), HLA-B (27% identical), HLA-G (27% identical), MR1 (25% identical), FCGRT (23% identical), AZGP1 (22% identical), CD1B (17% identical), and 10 more.
Diseases named in the same sentence as MICA in open-access papers:
MICA is named in the same sentence as 225 diseases in open-access papers, as found by Europe PMC text mining. Sharing a sentence is not in itself a finding about the gene and the disease. The quoted sentences say what the papers report.
melanoma (92 papers, 2009 to 2026). A malignant, usually aggressive tumor composed of atypical, neoplastic melanocytes. "More recently, it was shown that melanoma-derived exosomes negatively affect NK cell function, as they contain melanoma-associated antigens, MICA, and death ligands such as FASL and TRAIL." (PMID 34572949, 2021). "MICA*009 allele has also been found in a high frequency in melanoma patients compared with controls." (PMID 33868281, 2021). "In contrast, null associations were reported in studies that examined associations between the MICA A5.1 polymorphism and colorectal cancer, gastric cancer, and melanoma." (PMID 31166958, 2019). "Together, these results indicate that melanoma-associated fibroblasts secrete high levels of active MMPs leading to a decrease of MICA/B expression at the membrane of tumor cells." (PMID 28423623, 2017). "In a first analysis, we found a positive association of MICA*009 allele with cutaneous malignant melanoma." (PMID 25838620, 2015). "Remarkably, a limited number of studies concerning the polymorphism in MICA gene transmembrane region have been carried out in melanoma disease." (PMID 25838620, 2015). "In the present work, we have investigated for the first time the influence of MICA polymorphism in the extracellular domains on melanoma disease in a group of patients with cutaneous malignant melanoma from southeastern Spain." (PMID 25838620, 2015). "We now observe that ADAM10 acts as sheddase of melanoma cell–associated MICA." (PMID 39837817, 2025). "Furthermore, MMP inhibitor restored the presence of MICA/B on the melanoma cell membrane, thereby enhancing their susceptibility to NK cell-mediated destruction." (PMID 40399946, 2025). "We show that MICA is predominantly retained intracellularly in melanoma cells and colocalizes with the endoplasmic reticulum chaperone calreticulin (CRT)." (PMID 41683735, 2026). "Melanoma cells release soluble ligands such as the major histocompatibility complex class I chain-related protein A (MICA) and B (MICB)." (PMID 40940929, 2025). "Confocal microscopy analysis further confirmed these findings, as a deep and specific signal from MICA/B fluorescence is seen in the extra-nuclear compartment of untreated melanoma cells." (PMID 39837817, 2025). "Specific blockade of ADAM10 or androgen receptor impairs the androgen-induced MICA shedding and melanoma immune-escape." (PMID 39837817, 2025). "By combining different experimental approaches, we observe that melanoma escape is mediated by the androgen-triggered shedding of the surface molecule MICA." (PMID 39837817, 2025). "Melanoma cell lines have been found to exhibit increased levels of NKG2D ligands MICA/B, which play a crucial role in activating NK cells during interactions with melanoma cells." (PMID 40805135, 2025). "Our results showed that CCNB1 knockdown led to an upregulation of MICA/MICB expression in melanoma cells, and a corresponding increase in NKG2D expression in NK-92MI cells." (PMID 40430484, 2025). "An increase in soluble forms of MICA/B (sMICA/B) has been detected in serum from melanoma patients, which correlates with poor survival in response to ipilimumab (anti-CTLA-4 mAb) treatment." (PMID 39837817, 2025). "Further, the increase in MICA serum levels correlates with a poor outcome in melanoma patients treated with the anti-PD-1 monoclonal antibody, pembrolizumab." (PMID 39837817, 2025). "Specific blockade of ADAM10 by GI254023X inhibits the hormone effect on MICA expression in melanoma cells and prevents its release, thus counteracting the androgen-induced immune escape." (PMID 39837817, 2025). "When supernatants of primary NK cells and sNK cells were used to treat melanoma tumors, sNK supernatants induced a higher increase of MICA/B on tumors compared to the primary NK cell supernatants." (PMID 40805135, 2025).
melanoma (continued). "Our results show that androgens reduce frequency and expression of the surface NKG2D ligand MICA/B in melanoma cells, with a simultaneous increase in sMICA levels." (PMID 39837817, 2025). "For example, the IRE1α-XBP1s pathway downregulated the expression of the NK group 2D (NKG2D) ligand MHC class I polypeptide-related sequence A (MICA) in human melanoma cells under ER stress conditions." (PMID 41372991, 2025). "The IRE1α-XBP1 arm represses the expression of the NKG2D ligand MHC class I polypeptide-related sequence A (MICA) in human melanoma cell lines undergoing ER stress." (PMID 38291473, 2024). "Clinical data demonstrated that higher serum soluble MICA of melanoma patients indicate less benefits following immunotherapy with T‐cell checkpoint blockade, indicating that MICA/B shedding is a new therapeutic target in cancer immunology." (PMID 38882209, 2024). "Metastatic melanoma cells frequently shed NKAR-activating ligands such as the NKG2D ligands MICA and MICB." (PMID 38067178, 2023). "While both soluble ULBP2 and MICA were elevated in melanoma patients, only soluble ULBP2 correlated with worsened survival." (PMID 37626965, 2023). "Cancer cells stimulate CAFs, and the high level of MMPs secretion by CAFs in melanoma TME decreases the MICA/B expression, which prevents the activation of NK cells." (PMID 38057843, 2023). "For example, the treatment of human melanoma cells with IFN-γ reduces MICA levels, and TGF-β downregulates the transcription of MICA, ULBP2, and ULBP4 in human malignant gliomas." (PMID 37603573, 2023). "After examining different melanoma cells, it was discovered that MICA/B and ULBPs are extensively present in melanoma cells." (PMID 38057843, 2023). "Secreted MICA on the other hand impairs NK and CD8+ T cell responses, and a human melanoma cell line expressing the MICA allele *008 has been shown to release MICA in association with EVs." (PMID 36081494, 2022). "We discovered that epigenetic modifiers, Entinostat, Decitabine, Ricolinostat and Vorinostat increased the expression of MICA/MICB on the cells in melanoma–fibroblast bicellular spheroids." (PMID 35731974, 2022). "In melanoma, MICA expression was negatively regulated by the production of interferon-gamma mediated by the activity of STAT1." (PMID 35565467, 2022). "In melanoma treated with Ipilimumab, lower baseline soluble major histocompatibility complex class I chain-related protein A (MICA), lower soluble CD25, and a significant rise in soluble CD163 correlates with higher irAEs." (PMID 35558065, 2022). "For example, due to its expression on exosomes, previous studies inferred that exosomal MICA derived from metastatic melanoma cell line (Ma- Mel-86c) is responsible for the NKG2D downregulation." (PMID 35031075, 2022). "The baseline concentration of IFNγ-inducible chemokine CXCL10 was higher in melanoma, whereas higher serum concentrations of MICA and MICB-both soluble NKG2D ligands-were detected in UC." (PMID 34071888, 2021). "MICAB1 PBD1G-ADCs also increased the survival of C57BL/6 mice receiving injections of MICA-transfected B16F10 melanoma cells, and the cured mice developed long-term protective immunity when rechallenged with B16F10 MICA*001." (PMID 35967081, 2021). "In fact, studies have shown that the shedding of activating ligands, such as MICA and UBLP2, is associated with lower survival in stage IV melanoma patients." (PMID 33802954, 2021). "Accordingly, we observed that several melanoma cell lines and metastatic melanomas display an intracellular pool of MICA but only some of them exhibit cell surface MICA." (PMID 34394116, 2021). "Melanoma cells very often display some ligands for NKG2D (MICA/B and ULBP), while the presence of less-characterized NCR ligands seems to be high in early disease stages." (PMID 33138017, 2020).
melanoma (continued). "Upregulation of MICA on melanoma and colorectal cancer cell lines by treatment with HDACi FR901228 or butyrate, was significantly inhibited by HC treatment, resulting in reduced binding of NKG2Dfc soluble receptor, as shown in FM78, FM86, and SK-MEL28." (PMID 32849657, 2020). "Vesicular stomatitis virus (VSV) has been shown to dramatically increase MICA mRNA expression upon infection of Jurkat T cells; however, surface MICA protein expression is decreased on infected Jurkat T cells and melanoma cell lines." (PMID 33352921, 2020). "In a recent study using a murine model, antibodies blocking MICA secretion by tumors while simultaneously activating NK cells were shown to be therapeutic in a model of melanoma." (PMID 32656081, 2020). "Expression of CEACAM1-4L on the surface of melanoma cells reduces the expression of MICA, ULBP2, CD155 and CD112 via matrix metalloproteinase (MMP)-mediated shedding of these ligands, resulting in escape of NK cell mediated killing." (PMID 30871206, 2019). "HD and melanoma patient sera were tested for immunosuppressive factors MICA, NT5E/CD73 and tactile/CD96, as well as perforin, which is released by cytotoxic NK and T cells and is a surrogate biomarker for in vivo cytolytic activity of these effectors." (PMID 30761123, 2019). "Neutralising MICA was effective only for melanoma cells, which release soluble MICA in high doses in a platelet-independent manner." (PMID 30908480, 2019). "Nevertheless, the treatment of melanoma cells with 1 mM VPA has been shown to induce only MICA, MICB and ULBP-2, mediated by the ERK pathway, which is also consistent with our results using Panc89 and PC-3 tumor cells." (PMID 30972064, 2019). "Platelet cloaking induced the release of MICA from all cell lines, however this only reached significance for our melanoma cells." (PMID 30908480, 2019). "This perhaps suggests that the high trafficking melanoma cells release high concentrations of soluble MICA to evade NK cell detection and attack, providing an explanation for the lesser capacity of NK cells to mount an immune response to this cell line." (PMID 30908480, 2019). "The strongest effect was observed for MICA expression on the melanoma cell line and for MICB on the 59M ovarian cells, which expressed the highest basal levels of their respective ligands." (PMID 30908480, 2019). "Once the exosomes from the melanoma cell line Ma-Mel-86c had been characterized phenotypically and functionally, the expression of MICA within these nanovesicles was analysed by ELISA." (PMID 29720199, 2018). "As shown, endogenous MICA was present in melanoma-derived nanovesicles, but was much less abundant than tetraspanins." (PMID 29720199, 2018). "Further, we use a model in which MICA protein is expressed endogenously in vesicles secreted by melanoma cell lines and demonstrate that they are functionally active, down-modulating the receptor NKG2D on lymphocytes." (PMID 29720199, 2018). "Melanoma exosomes were incubated with the detection antibody anti-MICA conjugated to AuNP for different times prior to the run on the strip." (PMID 29720199, 2018). "The immunomodulatory properties of anti-MICA/B-PBD were assessed in MICA-transgenic mice engrafted with MICA- expressing mouse melanoma B16-F10." (PMID 30400835, 2018). "With regard to the mechanism of inhibition, our data provide evidence that melanoma-associated fibroblasts, though the secretions of active MMPs, decrease MICA/B expression at the surface of melanoma tumor cells." (PMID 28423623, 2017). "Melanoma cells contrive resistance to NK cell-mediated death by increasing the expression of HLA class I molecules and decreasing the expression of MICA and NCR, which are ligands that induce cytotoxic activities of NK cells." (PMID 28286532, 2017). "Melanoma immunoediting by NK cells increases expression of MHC I, or downregulates NK ligands supported by the decreased expression of MICA reported in metastatic versus primary melanoma." (PMID 29276510, 2017).
melanoma (continued). "NK1.1− CD4+ NKG2D+ or NK1.1+ CD4+ NKG2D+ cells were incubated with melanoma target cells, B16‐MICA, which ectopically expressed MICA of B16 cells." (PMID 28224733, 2017). "Statins were also found to increase MICA expression on melanoma cells in vitro and melanoma growth as well as pulmonary metastases in mice." (PMID 27907087, 2016). "The analysis of MICA expression on melanoma lesions revealed a higher expression in primary melanoma than in metastatic melanoma." (PMID 26779186, 2015). "A limited number of studies have been performed so far on the polymorphism in the transmembrane region (exon 5) of the major histocompatibility complex class I chain-related gene A (MICA) in patients with melanoma." (PMID 25838620, 2015). "In the present study, we analyzed statins’ ability to regulate MICA expression in human melanoma cells and the consequences of this treatment on melanoma development." (PMID 23493799, 2013). "We demonstrated that treatment of two human melanoma cells with atorvastatin or lovastatin induced a weak but reproducible MICA membrane overexpression, provoking an increase of melanoma cell sensitivity to NK cell lysis in vitro." (PMID 23493799, 2013). "Our data shows that treatment of two human melanoma cell lines with statins induced a weak but significant increase of MHC class I Chain-related protein A (MICA) membrane expression." (PMID 23493799, 2013). "Altogether, this data shows that statin treatment of human melanoma cells enhanced MICA protein and membrane expression and that these treatments were not toxic, but increased the sensitivity of the tumor cells to NK-induced cell death in vitro." (PMID 23493799, 2013). "The level of MICA expression in melanoma samples correlated with XBP1s expression." (PMID 41372991, 2025). "MICA is an NKG2D ligand that has been reported to be strongly expressed in melanoma cells." (PMID 38067178, 2023). "Thus, we can conclude that MICA secretion was low in BRAF-WT melanoma both in EVs, and as soluble protein." (PMID 36726591, 2022). "Since quantification of EV-associated NKG2D-L is challenging to perform directly in supernatants, we initially characterized the effects of BRAFi and MEKi, alone and in combination, on EV-released MICA, separated from the soluble form by sequential centrifugations of melanoma cell conditioned media." (PMID 36726591, 2022). "The immunosuppressive TME of these 3D models is resulted not only from tumour cells but also from CAFs, lymphocytes and myeloid cells, accompanied by high expression of PD‐L1 and PD‐L2 with reduced expression of MICA/B, similar to those in patient melanoma tissues." (PMID 35731974, 2022). "Similarly, MMP‐9 also eliminates MICA/B expression in melanoma cells, evading T‐cell recognition for killing." (PMID 34486239, 2021). "Interestingly, in melanoma cell lines, the downregulation of MICA and ULBP2/5/6 induced by vemurafenib was counterbalanced by the addition of HDACi, potent NKG2D ligand inducers, to the in vitro culture, leading to enhanced NK cell activity." (PMID 33572396, 2021). "Of all the NKG2D ligands, MICA was shown to be highly expressed in melanoma." (PMID 33802954, 2021). "All primary melanoma cells consistently expressed the stress-induced NKG2D ligand MICA/B." (PMID 34187852, 2021). "In addition, a strong vaccination effect was obtained with MICA-ADC in a syngeneic MICA-transfected melanoma model." (PMID 35967081, 2021). "By contrast, tumor biopsy specimens from patients with head and neck squamous cell carcinoma (HNSCC), mesothelioma, ovarian, endometrial cancers, breast and melanoma were stained with the anti-MICA/B Mia4 mAb, revealing high levels of MICA/B expression in tumors." (PMID 35967081, 2021).